PIK3CA (phosphatidylinositol-4,5-bisphosphate 3-kinase catalytic subunit alpha)
Diseases named in the same sentence as PIK3CA in open-access papers (continued):
Sharing a sentence is not in itself a finding about the gene and the disease.
breast cancer (continued). "An Egyptian study found a correlation between T>G and T>C substitutions regarding PIK3CA variants in breast cancer patients and suggested that the oxidative damage accumulation due to age could induce these specific substitutions." (PMID 35875117, 2022). "In 2019, the US FDA approved the administration of alpelisib in combination with fulvestrant for the treatment of metastatic breast cancer patients with hormone receptor-positive, HER2-negative breast cancer possessing PIK3CA-mutations, following disease progression on or after endocrine therapy." (PMID 35055414, 2022). "In addition, PIK3CA-mutations are considered an early event in breast cancer development since they were detected even in small tumours as well as in non-invasive precursor lesions, like DCIS." (PMID 36279023, 2022). "PIK3CA (38%), the highly mutated gene in breast cancer, could produce the highest number of neoantigens per gene." (PMID 35387130, 2022). "In a breast cancer study, its expression was associated with PIK3CA mutation and PFS; nonetheless, its role in cancer has largely been unknown." (PMID 36389725, 2022). "Therefore, the PIK3CA mutation status plays a vital role in determining the optimal treatment choice for breast cancer patients." (PMID 35719907, 2022). "Collectively, these data suggest that the therapeutic targeting of MLL1- and KMT2D/MLL4-directed H3K4 methylation may be beneficial HR+, PIK3CA-mutated, breast cancer." (PMID 36970726, 2022). "For HER2 positive breast cancer, PIK3CA mutations are associated with worse prognosis." (PMID 36010585, 2022). "According to a clinical study published on Breast Cancer in 2021, compared to the TCGA datasets, which mainly consist of data from patients with breast cancer in western countries, the prevalence of PIK3CA mutation in patients with breast cancer in China is higher (45.6% vs. 34.7%, p < 0.001)." (PMID 38089455, 2022). "An ISFET (ion-sensitive field effect transistor) sensor that is mainly used for pH measurement as a chemical sensor was utilized to detect PIK3CA mutations by monitoring hydrogen ion generation during the loop-mediated isothermal amplification (LAMP) of DNA samples of breast cancer cell lines." (PMID 35053452, 2022). "Interestingly, PIK3CA is the most frequently mutated gene in the TCGA breast cancer cohort (32%), and its mutation frequency in the luminal B subtype of breast cancer is 29%." (PMID 35013309, 2022). "Besides, PI3Kα inhibitor alpelisib is suitable for breast cancer patients with PIK3CA mutations detected by the PIK3CA RGQ PCR kit." (PMID 36302755, 2022). "However, the mutation frequency of PIK3CA, which is commonly mutated in breast cancer, in IMPC was only 12% (2/17)." (PMID 35013309, 2022). "Plasma sequencing using next-generation sequencing is an emerging companion diagnostic technology for various indications such as BRCA1/2 testing in ovarian cancer, ALK rearrangements in lung cancer and PIK3CA gene mutations in breast cancer patients eligible for treatment with alpelisib." (PMID 36428589, 2022). "Similarly, low expression levels of PIK3R1, the gene encoding the regulatory subunit of PIK3CA (p85α), have been associated to poor prognosis, in particular in breast cancer." (PMID 36110934, 2022). "The US FDA recently approved the Therascreen PIK3CA RGQ polymerase chain reaction assay as a companion diagnostic for detecting PIK3CA breast cancer mutations in both tissue and liquid biopsies, suggesting future applications for liquid breast cancer biopsy in clinical decision-making." (PMID 35884530, 2022). "Following a successfully phase III clinical study, the FDA approved the first PI3K inhibitor, Piqray (alpelisib), for breast cancer patients with advanced disease and where their tumors have the PIK3CA mutation and are hormone receptor (HR) positive and HER2 negative in 2019." (PMID 36221123, 2022).
breast cancer (continued). "Moreover, the combination therapy using Aplelisib and Fulvestrant has become the first choice for treatment of postmenopausal HR + /HER2- breast cancer patients with PIK3CA mutations." (PMID 35778737, 2022). "In addition, US images are easily available to monitor for PIK3CA mutations throughout the treatment period of breast cancer." (PMID 35719907, 2022). "PIK3CA activation mutations are identified in multiple tumor types, such as breast cancer, uterine corpus endometrial carcinoma, carcinoma of the uterine cervix, colorectal carcinoma, esophageal carcinoma, gallbladder carcinoma, non-small cell lung cancer, ovarian carcinoma, and gastric cancer." (PMID 35402264, 2022). "PIK3CA appears the most frequently mutated gene in 37.8% of these breast cancers." (PMID 34975329, 2022). "Most methionine-dependent breast cancer cell lines harbor a PIK3CA genomic mutation and decreased expression of SLC7A11, which is a gene that encodes a cystine transporter also known as xCT that is correlated with increased methionine dependency in breast cancer cells." (PMID 36432434, 2022). "It has received FDA approval in May 2019 for patients with metastatic HR-positive breast cancer with PIK3CA mutation who have received prior endocrine therapy." (PMID 36338738, 2022). "Importantly, polymorphisms in PIK3CA have been reported as being related to different effects of aspirin in breast cancer treatment." (PMID 35457144, 2022). "Results from an updated BYLieve Cohort A analysis demonstrate the ongoing benefit of alpelisib plus fulvestrant in patients with HR-positive, HER2-negative, PIK3CA-mutated advanced breast cancer whose disease progressed on or after treatment with a CDK4/6 inhibitor plus an aromatase inhibitor." (PMID 35348782, 2022). "Importantly, PIK3CA mutations confer resistance to BRD4 inhibition in breast cancer, which can be reversed using PIK3CA-specific or mTOR inhibitors." (PMID 36139513, 2022). "Furthermore, the PI3K pathway appears to be associated with resistance to anti-HER2 therapies, and PIK3CA mutations have been described in a variable percentage of HER2-positive breast cancer." (PMID 35740668, 2022). "PIK3CA mutations in breast carcinoma are the most prevalent." (PMID 36539659, 2022). "Mutations in PIK3CA gene are detected in approximately 9% of TNBC, including triple negative metastatic recurrence from primary HR+ breast cancer that may retain PIK3CA mutation." (PMID 36579519, 2022). "PIK3CA is the most frequently mutated gene across ductal and lobular breast carcinomas." (PMID 34058066, 2022). "In human breast cancer, somatic mutation of PIK3CA has been found in 8–40% of case samples." (PMID 34359206, 2021). "The response rates were 2% for complete responses (CR: olaparib for BRCA2 mutation and high HRD score in prostate cancer, and capivasertib for PIK3CA mutation in breast cancer), 17% for partial responses (PR), 16% for stable disease (SD), and 65% for progressive disease (PD)." (PMID 34006291, 2021). "Moreover, PIK3CA in residual disease after neoadjuvant chemotherapy is associated with poor survival in breast cancer, suggesting PIK3CA as a prognostic biomarker in breast cancer." (PMID 34367282, 2021). "PIK3CA mutation has been reported in 7.1 to 35.5% of all breast cancers, while up to 13% of breast cancers may have copy number gain in this gene." (PMID 34769309, 2021). "Despite these limitations, here we confirm the presence of recurrent PIK3CA mutations in JP and provide evidence that JP and coexisting carcinoma are clonally related, further expanding our understanding of the relationship between JP and breast cancer." (PMID 33263939, 2021).
breast cancer (continued). "Of these, PIK3CA mutation is the most common and independent event in breast cancer." (PMID 34415239, 2021). "Oncogenic mutations in PIK3CA are found in approximately 25% of breast cancers." (PMID 33618712, 2021). "Additionally, there are even FDA approved drugs available for some of the discovered alterations, such as trastuzumab for ERRB2 amplifications or alpelisib for PIK3CA mutations in breast cancer." (PMID 34200508, 2021). "For example, PIK3CA H1047R is a driver mutation in breast cancer, suggesting that it could be a ctDNA specific to breast cancer." (PMID 34868925, 2021). "Patients with HER2‐positive breast cancer bearing PIK3CA mutations might benefit from this category of drug." (PMID 33665980, 2021). "Mutations in the PIK3CA gene were found in a wide range of human cancers including glioblastoma, gastric cancer, lung cancer, colorectal cancer, and breast cancer." (PMID 34359206, 2021). "PIK3CA mutations were more likely to be detected in patients over 40 years old (P = 0.002), those who are postmenopausal (P = 0.004), and had ER-positive (P = 0.002), and PR-positive (P = 0.012) types of breast cancer." (PMID 34093841, 2021). "Phase III trials have suggested that PIK3CA mutations may be predictive of response to PI3K inhibitor therapy in oestrogen receptor positive breast cancer." (PMID 33799597, 2021). "For example, Alpelisib, which is a new anticancer drug and is clinically beneficial to PIK3CA-mutated breast cancer patients, might be a future medicine for dogs with mammary tumors." (PMID 34359206, 2021). "The PI3K pathway is hyperactivated in 70% of breast cancers and 20–40% have PIK3CA mutations." (PMID 33435254, 2021). "PI3K is commonly activated in breast cancer by PIK3CA mutations." (PMID 34833123, 2021). "In addition, 38 breast cancers were predicted into 12 high-risk and 26 low-risk cases based on the extended concurrent genes signature, while the pathogenic PIK3CA variant (rs121913279) was significantly mutated between groups." (PMID 34203389, 2021). "In addition, ER+ breast cancer with PIK3CA activating mutations and 11q13-14 amplification have poor survival with unclear mechanism." (PMID 34131114, 2021). "The prognostic impact of PIK3CA mutation in breast cancer is still controversial." (PMID 34093841, 2021). "For instance, in a cohort of patients with metastatic PIK3CA-mutated breast cancer treated with fulvestrant and palbociclib, a posttreatment decrease in plasma ctDNA PIK3CA levels below the median at cycle 1, day 15, compared with baseline levels was associated with improved PFS." (PMID 34056539, 2021). "A very recent preclinical study in fact showed that regression of HER2-positive breast cancer PDX models with the potent H1047 PIK3CA mutations could only be achieved with the addition of everolimus to neratinib, but not with neratinib alone." (PMID 34045483, 2021). "In addition, alpelisib, an alpha-specific PI3K inhibitor (PI3Ki), has recently been approved for the treatment of PIK3CA-mutated ER+ advanced breast cancer that progressed on previous endocrine therapy." (PMID 34433817, 2021). "Notably, treatment with alpelisib not only interfered with PIK3CA-mediated downstream signaling, but also induced a dose-dependent decrease in p110α protein levels in ER+/PIK3CA-mutated breast cancer cell lines, suggesting a dual mode of action." (PMID 34298731, 2021). "Ras and Pik3ca mutations are mutually exclusive in endometrial and breast cancers, but co-exist in colorectal and lung tumors, suggesting that the acquisition of both mutations may confer additional characteristics that are beneficial for the tumor." (PMID 34356110, 2021).
breast cancer (continued). "However, a proportion of HER-2-amplified breast cancers continue to develop drug resistance, eventually due to phosphatase and tensin homolog loss and the activation of PIK3CA mutations." (PMID 33672204, 2021). "In addition, activating PIK3CA mutations in basal-like breast cancer were found to induce paracrine activation of AREG/EGFR/ERK signaling." (PMID 34207383, 2021). "Furthermore, breast cancers in general upregulate the PI3K signaling pathway through the expression of constitutive active or amplification of PIK3CA and deletion of PTEN or INPP4B or Akt mutations." (PMID 34917906, 2021). "INPP4B expression was also significantly higher in breast cancers with multiple PIK3CA mutations." (PMID 34035258, 2021). "In HER2+ breast cancer cell lines mutated for PIK3CA, as well as in patient-derived xenograft models, MEN1611 seemed to act synergistically when associated with trastuzumab, also inducing a dose-dependent p110α protein depletion and a pro-inflammatory phenotype compatible with p110γ inhibition." (PMID 34298731, 2021). "PIK3CA mutations have also been reported in several malignancies such as breast cancer, head and neck cancer, glioblastoma, gastric cancer, lung cancer, prostate cancer, anal canal cancer, hepatocellular cancer, colorectal cancer, endometrial cancer, and cervical cancer." (PMID 34012039, 2021). "The phase III placebo-controlled SOLAR-1 trial randomized 572 patients with endocrine-resistant advanced breast cancers who had received prior AI in the neoadjuvant/adjuvant or metastatic settings, including 341 patients with PIK3CA mutation, to fulvestrant with either alpelisib or placebo." (PMID 34769309, 2021). "The PIK3CA H1047R mutation has been known to gain-of-function mutation stimulating catalytic activity, and expression of PIK3CA H1047R induced tumor initiation, cell dedifferentiation, tumor heterogeneity, and invasiveness and migration in mammary tumor cells." (PMID 34359206, 2021). "According to the readout of the PIK3CA mutation screen, we speculated that HER2+ mammary cancer cells harbouring PIK3CA mutations might exhibit resistance to lapatinib treatment." (PMID 34842356, 2021). "The other 11 patients had progressive disease (PD), and eight of them harboured PIK3CA mutations, which indicated that the anti‐HER2 treatment effectiveness was limited for advanced HER2+ breast cancer patients with PIK3CA mutations than for those with PIK3CA‐WT (100% vs." (PMID 34842356, 2021). "Similarly, clinical studies in HER2-positive breast cancers have found that patients with mutations in PIK3CA experience decreased benefit from neoadjuvant trastuzumab." (PMID 32525891, 2020). "Our results are in contrast to evidence on colorectal cancer, which show benefits of aspirin for PIK3CA mutated tumors and may suggest different biological pathways at work in breast cancer carcinogenesis." (PMID 32326897, 2020). "Breast cancers with a PIK3CA mutation have a good prognosis." (PMID 33004031, 2020). "Finally, in the METABRIC and TCGA datasets, PRR11 amplification and PIK3CA mutations were mutually exclusive of each other in ER+ breast cancers." (PMID 33127913, 2020). "Loss of PIK3R1 is an effective therapeutic mechanism for PIK3CA‐positive breast cancers." (PMID 32419250, 2020). "It is unclear whether the presence of PIK3CA mutations might affect the clinical response of HER2-positive breast cancer patients undergoing treatment with HER2-targeting agents." (PMID 32210163, 2020). "Similarly, AKT1 and PIK3CA mutations harbored relatively higher VAFs in our Chinese breast cancer cohort." (PMID 33173047, 2020).
breast cancer (continued). "In addition, the higher mutation frequencies of PIK3CA in benign CMTs, compared with malignant CMTs and human breast cancers, highlight the early oncogenic roles of PIK3CA mutations." (PMID 32680987, 2020). "PIK3CA mutations were detected in a cholangiocarcinoma patient and a breast cancer patient." (PMID 32738923, 2020). "Similarly, SGK3 was also found to be a key mediator of PDPK1‐dependent melanomagenesis and a driver for tumour formation in breast cancer cells in both PIK3CA wild‐type and mutated cells in an AKT‐independent manner." (PMID 32926495, 2020). "PIK3CA mutations were identified in 36% of patients with HR+/HER2- breast cancer." (PMID 32326897, 2020). "Seven out of ten (70%) breast cancers harboured a PIK3CA mutation in at least one tumour component." (PMID 32058674, 2020). "Combination therapy of a HER2 inhibitor and an AKT inhibitor, as well as other PI3K pathway inhibitors, could overcome the therapeutic limitations associated with single-agent anti-HER2 treatment in PIK3CA-mutant HER2+ breast cancer cell lines." (PMID 33303839, 2020). "In the SOLAR-1 Phase III clinical trial, patients with PIK3CA-mutated ER+/HER2− breast cancer had almost a doubling in PFS in response to the p110α-selective PI3K inhibitor alpelisib (BYL719) (Piqray®) in combination with fulvestrant compared to patients treated with fulvestrant with placebo." (PMID 32795346, 2020). "Thus, mutant PIK3CA is an example of an altered gene that is associated with changes in drug responses across multiple subtypes of breast cancer." (PMID 32525891, 2020). "A splice site driver mutation in PTEN co-occurred in HSC-4 and may have counteracted the oncogene addiction effect on the mutated PIK3CA, as suggested previously in breast cancer." (PMID 32990596, 2020). "However, Shah and coworkers have challenged this role of PIK3CA mutations in lobular breast cancer progression." (PMID 32210163, 2020). "Interestingly, while the selective p110α inhibitor alpelisib (BYL719) generated a positive response in PIK3CA mutant breast cancer, the additional loss of PTEN induced reactivation of p110β signalling and caused resistance to this targeted therapy." (PMID 33276499, 2020). "The presence of PIK3CA mutations was associated with low A3A mRNA expression in breast cancer." (PMID 32176735, 2020). "For instance, the phenotypic manifestations of CLOVES syndrome, which is characterized by tissue overgrowth and complex vascular anomalies that result from the activation of PIK3CA mutations, can be ameliorated by the PIK3CA inhibitor alpelisib, which was developed and approved for breast cancer." (PMID 32066498, 2020). "More than 70% of breast cancer cases have PIK3CA gene mutations, and the mutated PIK3CA gene can cause the activation of the PI3K/AKT pathway, which subsequently leads to rapid proliferation and invasion of breast cancer cells, probably ending up with metastasis." (PMID 33817238, 2020). "The Qiagen Therascreen® PIK3CA RGQ PCR Kit for the detection of 11 mutations in the PIK3CA gene in ctDNA and/or tumor tissue received U.S. regulatory approval for use in guiding treatment decisions in patients with breast cancer undergoing treatment with Alpelisib." (PMID 32785174, 2020). "Activation of Akt is usually associated with a pro-tumour phenotype; however, recent work has suggested that elevated pAkt may be associated with a good prognosis in luminal A ER-positive breast cancer, particularly within the context of PIK3CA mutations." (PMID 33298139, 2020).